HIF1A (hypoxia inducible factor 1 subunit alpha)
Diseases named in the same sentence as HIF1A in open-access papers (continued):
Sharing a sentence is not in itself a finding about the gene and the disease.
cancer (continued). "HIF-1 was found to be a major regulator of oxygen homeostasis and of aerobic glycolysis in cancer (Warburg effect), and HIF-1α its inducible subunit." (PMID 30211123, 2018). "MCT4 expression is induced by hypoxia via hypoxia-inducible factor 1 alpha (HIF-1α) and is thus of particular interest in cancer." (PMID 30540938, 2018). "Other studies in cancer cells have shown that HIF-1α-induced lincRNA-p21 bind HIF-1α and VHL and thus disrupt the VHL–HIF-1α interaction and promote HIF-1α accumulation." (PMID 29383635, 2018). "The level of HIF-1α is much higher in the whole extract of both cancer cell lines compared to immortalized normal breast cells." (PMID 29584711, 2018). "In cardiomyocytes and cancer cells, HIF1α has been reported to activate PPARγ.107, 108 In pulmonary vascular cells, PPARγ is reportedly subject to HIF1-dependent and HIF1-independent adjustment." (PMID 29929789, 2018). "Carbonic anhydrase IX (CAIX) plays a key role in pH regulation in hypoxic cancer cells as its expression is induced by hypoxia via HIF-1α." (PMID 30061885, 2018). "HIF-1α is often stabilized and activated in cancer tissues and inhibiting HIF-1α's transcription activity has great potential to develop novel cancer therapeutics." (PMID 29732373, 2018). "Selective HIF1α inhibitors are not readily available, although there is interest in targeting the HIF1α activation pathway for cancer therapy." (PMID 29456535, 2018). "VEGF-A expression increased in endothelial and cancer cells under the hypoxic conditions induced by HIF-1α stabilization." (PMID 29976150, 2018). "Under such conditions, several transcription factors (such as AP-1, Ets1, and hypoxia-mediated HIF1α [HIF1α]) are known to directly upregulate Ets1 transcription in cancer cells." (PMID 30467308, 2018). "HIF-1α regulates the expression levels of various chemokines and their receptors to promote the proliferation and metastasis of many cancers." (PMID 30258464, 2018). "Cancer-induced hypoxia-inducible factor-1α (HIF-1α) plays a key role in the over-expression of glucose transporters and glycolytic enzymes." (PMID 29609556, 2018). "Mitochondrial biogenesis and DNA fragmentation of prostate cancer cells have lesser HIF1α in cancer cells." (PMID 30445746, 2018). "Under hypoxia conditions, HIF-1α induces activation of autophagy in cancer progression and regulates many of its target genes." (PMID 30400561, 2018). "HIF-1α mediates the metabolic switch from oxidative phosphorylation to aerobic glycolysis in cancer cells and immune cells in the TME." (PMID 30151352, 2018). "As regards cancer, first hints for a HIF-1α/Notch crosstalk came from a transcriptomic analysis showing the upregulation of Notch target genes in hypoxic neuroblastoma cells." (PMID 29996493, 2018). "An integral part of the metabolic adaptation towards OR due to a hypoxic microenvironment in cancer cells is the HIF1α mediated gene expression involved in shifting the metabolism towards anaerobic glycolysis." (PMID 29402948, 2018). "Dysregulation of Stat3 signaling is known to enhance tumorigenic potential of cancer cells by increasing expression levels of angiogenesis markers, such as HIF-1α and the vascular endothelial growth factor (VEGF)." (PMID 30583572, 2018). "For example, the use of chetomin, a chemical HIF1α inhibitor, can disrupt the interactions between this molecule and p300, attenuate hypoxia-induced gene expression, and increase radiosensitivity of cancer cells under severe hypoxic conditions." (PMID 29688867, 2018). "HIF1α-driven aerobic glycolysis in stromal cells supports cancer cell growth via the paracrine production of nutrients (such as lactate), which cancer cells can recycle." (PMID 29434587, 2018). "In previous studies, V-ATPase inhibitors were shown to increase HIF-1α levels in a different PCa cell line, PC-3, as well as in other cancers." (PMID 29988966, 2018).
cancer (continued). "Hypoxia, through HIF-1α, is known to regulate the expression of many proteins involved in collagen expression in cancer cells." (PMID 30487436, 2018). "In our study, HIF-1α siRNA silencing significantly reduced the proliferation, migration, and invasion abilities of cancer cells." (PMID 29899167, 2018). "In many cancers, HIF-1α is not only activated by low oxygen tension, but also amplified by a wide range of growth-promoting stimuli and oncogenic pathways." (PMID 29498688, 2018). "The non-glycolytic function of T454 phosphorylated PKM2, primarily involves the transcriptional co-activation of HIF-1α and β-catenin transcription factors to support cancer growth and drug resistance." (PMID 29468140, 2018). "The expression of HIF-1α aids in cell survival under low oxygen conditions and is found to be high in cancer cells inside solid tumors." (PMID 30002330, 2018). "Hypoxia enhances c-MET/HGF signaling by activating HIF-1α in several types of cancers such as lung, ovarian, and cervical cancers." (PMID 29560266, 2018). "Discorhabdins exhibit strong anticancer activities by inhibiting the interaction of the cancer target HIF-1α (hypoxia-inducible factor 1alpha) with p300." (PMID 30072656, 2018). "Another oncoprotein, which has been identified to be crucial in cancer cell survival and growth, especially under low-oxygen tension (hypoxia), is HIF-1α." (PMID 30234010, 2018). "In this regard, it should be mentioned that aberrant Receptor Tyrosine Kinase (RTK) signaling, which is frequently observed in human cancer, is at least in part responsible for the increased up-regulation of HIF-1α mRNA and/or protein expression." (PMID 29996493, 2018). "Studies have revealed that HIF-1α can promote cancer cell metastasis through EMT by upregulating snail, twist, and vimentin expression." (PMID 29661250, 2018). "For non-invasive imaging to identify hypoxia-induced cancer stem cells, HIF-1α aptamer-PEG-modified manganese magnetic nanoparticles, D-Fe3O4@Mn, were generated." (PMID 30029472, 2018). "It was displayed that the expression of around 20 genes is regulated by HIF-1α, including NFκB1, which is involved in regulation of inflammation and cancer." (PMID 30123433, 2018). "Upregulation of HIF-1α by RT can be a direct result of stabilizing HIF-1α in cancer cells, or it can occur indirectly as RT increases TAMs, which also stabilize HIF-1α." (PMID 30766539, 2018). "We demonstrated that the hypoxia inducible factor (HIF-1α) is present in cancer stem cells as well in differentiated cancer cells, while cancer stem cells express NANOG, which is a stem cell marker." (PMID 30424475, 2018). "The previous studies on cancer metabolism have shown that succinate can induce stabilization of the transcription factor HIF-1α." (PMID 29502308, 2018). "As hypoxia-inducible factor 1α, HIF-1α has been proved to be involved in the development and progression of various types of human cancers." (PMID 29899167, 2018). "These aHIF1α lncRNAs are induced under hypoxia in cancer cells to suppress HIF1A mRNA expression, thus providing for a HIF switch negative feedback loop." (PMID 29383635, 2018). "Several clinical studies describe the prognostic value of HIF-1α in cancer, including the elaboration of many meta-analyses for several kinds of cancer and different HIF-1α polymorphisms." (PMID 29942795, 2018). "Overexpression of HIF-1α is important in the activation the bunch of genes involved in cancer biology, encompassing cell proliferation, survival and apoptosis, glucose metabolism, erythropoiesis, as well as angiogenesis." (PMID 30123433, 2018). "Studies in cancer cells also show that hypoxia boosts the expression of fatty acid synthase and lipin-1 through HIF1α and the sterol regulatory element binding protein resulting in elevated fatty acid synthesis and lipid storage." (PMID 30374347, 2018). "Hypoxia-inducible factor-1α (HIF-1α) is a key transcription factor that controls dozens of target genes in a variety of cancers." (PMID 29466367, 2018).
cancer (continued). "HIF-1α is the oxygen-regulated subunit that has been studied in inflammation, diabetes, cardiovascular disease, and cancer." (PMID 29560266, 2018). "The oncogene-activated PI3K pathway, which is activated in many cancers, also stabilizes HIF1α even under normoxia." (PMID 30123774, 2018). "Previously, HIF-1α, a major mediator of hypoxia, has been reported in some malignant tumors to promote EMT24,31,32." (PMID 29515112, 2018). "Few reports, however, give some hints that the interplay of iron and HIF1α can bear significance for cancer biology." (PMID 30534534, 2018). "As HIF-1α was reported to upregulate the expression of HOTAIR at transcriptional level in hypoxic cancer cells, we examined the effect of HIF-1α overexpression on the level of HOTAIR in HeLa and C33A cells." (PMID 30355300, 2018). "2-DG has cytotoxic effects on different types of cancer cells, especially those overexpressing HIF-1α and with mitochondrial defects." (PMID 30234009, 2018). "It was suggested that HIF-1α activation led to autophagy and aerobic glycolysis, which would produce nutrients to surrounding cancer cells promoting their growth." (PMID 29896451, 2018). "The expression level of HIF-1α in the BxPC-3 cancer cell line increased in response to high glucose and CoCl2 concentrations." (PMID 30455857, 2018). "Previous studies performed with cancer cells have shown that, under hypoxic conditions, HIF-1α can stimulate the release of EVs with protumoral activities." (PMID 30206166, 2018). "In both cases, the ratios of PGC-1α to HIF-1α or MYC function as rheostats that will dictate the propensity of cancer cells to rely on glycolysis or OXPHOS for survival." (PMID 29629336, 2018). "Many regulatory molecules that are involved in EMT, including Snail, Dlx-2, HIF-1α, STAT3, TGF-β, Wnt, and Akt, have been implicated in the metabolic reprogramming of cancer cells." (PMID 30671168, 2018). "The first enzyme of the oxidative phase of the PPP, glucose-6-phosphate dehydrogenase (G6PD), is induced by HIF1α in several different cancer cell lines." (PMID 30374347, 2018). "Taken together, our results showed for the first time that PAC-1 induces HIF1α stabilization, DNA damage, and cell cycle arrest in cancer cells." (PMID 30287840, 2018). "The downstream target genes of HIF-1α are related to angiogenesis, cancer cell survival and invasion." (PMID 30560881, 2018). "Taken together, these studies suggest that HIF1α can act as a fundamental driver of both mitochondrial fission and cancer progression." (PMID 29337889, 2018). "HIF1a overexpression leads to upregulation of the numerous HIF1a target genes, many of which are also upregulated in cancer stem cells." (PMID 29883385, 2018). "We also found that expression of the HIF-1α PPAA mutant restored tumorsphere formation in P4HA1-silenced cancer cells." (PMID 30367042, 2018). "It is believed that HIF-1α, a critical transcriptional factor in response to hypoxia, is closely related to the chemoresistance of many malignant tumors." (PMID 29898734, 2018). "HIF-1α is a transcription factor that regulates cancer progression such as angiogenesis, metastasis, anti-apoptosis, cell proliferations whereby it imparts resistance to chemotherapy." (PMID 30037082, 2018). "Once HIF-1α is increased, it can promote cancer cell EMT by inducing expressions of downstream genes like Twist-1 and ZEB1." (PMID 29435158, 2018). "And overexpression of HIF-1α/HIF-2α was generally associated with short-term survival and increased mortality in cancer cases." (PMID 30135144, 2018). "In particular, hypoxic stress leads to the induction of HIF-1α in cancer cells which consequently upregulates CD39/CD73 and represses adenosine kinase, causing increased accumulation of adenosine in the extracellular space." (PMID 30627563, 2018). "Recently, many agents affecting HIF1α signaling have been introduced, leading to different results depending on a cancer HIFα phenotype." (PMID 30386298, 2018).
cancer (continued). "Instead, under hypoxia, HIF1α stabilization, despite the presence of SOX2, likely represents the leading factor that causes cancer cell metabolic switch to anaerobic glycolysis." (PMID 30466459, 2018). "Production of ROS by cancer cells inhibits PHD2 (with subsequent gain of function of HIF-1α) and enhances NO production by CAFs." (PMID 29434587, 2018). "Converging on the same pathway, hypoxia inducible factors (HIF1α) signal through the SGK3β/β-catenin axis promoting cancer cell stemness and immune suppression." (PMID 29871670, 2018). "In cancer cells, mutations in Krebs cycle enzymes result in accumulation of succinate, which via product inhibition inhibits the HIF hydroxylases, causing HIF-1α accumulation." (PMID 30175272, 2018). "Of note, the tumor suppressor gene TAp73 elicits anti-cancer effects by simultaneously blocking HIF-1α and the pro-inflammatory chemokines Ccl2, Cxcl1, Cxcl2, which are known to promote angiogenesis and leukocyte migration." (PMID 29996493, 2018). "Other studies also revealed that hypoxia-exposed cancer cells produce the higher levels of Gal-1, which was closely related to HIF-1α and carbonic anhydrase IX (CA IX) and knocking down Gal-1 can reduce hypoxia-induced invasion and migration of cancer cells." (PMID 29854732, 2018). "This phenotype can be driven by Hif1a and has been shown to be the preferred mode of migration of epithelial cancer cells to detach from the ECM and move through dense hypoxic conditions, providing a possible explanation for OSE stratification." (PMID 30418965, 2018). "Recently, studies have shown that the HIF-1A induced expression of PDK1 limits the oxidation of pyruvate to acetyl-CoA by inhibiting the pyruvate dehydrogenase complex in cancers of the breast and kidney." (PMID 30018740, 2018). "In cancer cells, an intricate network of pathways has been reported to control the abundance and transcriptional activity of HIF-1α." (PMID 30004423, 2018). "While HIF-1α functions in cancer progression have been increasingly recognized, the contribution of HIF-2α remains widely unclear despite accumulating reports showing its overexpression in cancer cells." (PMID 29721188, 2018). "Recent studies showed that the expressions of HLA-G mRNA and protein were upregulated in HLA-G-negative cancer cells via HIF-1α under hypoxic conditions." (PMID 30061885, 2018). "Since, EF24 was able to inhibit HIF-1α activity, it likely affects glucose metabolism, thereby regulating cancer cell survival." (PMID 30619754, 2018). "HIF1-α stabilization is the major response mechanism to hypoxia, and has been described in many cancer types." (PMID 30242167, 2018). "Previous reports have shown that tempol or other antioxidants can prevent HIF-1α-mediated cancer progression." (PMID 29433520, 2018). "HIF-1α participates in the pathogenesis of different types of malignancies by regulating the proliferation, migration, and invasion of cancer cells." (PMID 29899167, 2018). "High expression of HIF-1α protein in various cancers including cervical, head and neck and oropharyngeal carcinoma was correlated with an unfavorable prognosis." (PMID 30513863, 2018). "The responses to anti-cancer therapy using doxorubicin and ionizing radiation would be diminished because of HIF-1α upregulation." (PMID 30081604, 2018). "The connection between WWOX and cancer cell metabolism was established after linking WWOX protein to Hypoxia-inducible factor 1-alpha (HIF1α) function." (PMID 30619734, 2018). "HIF1-α is often overexpressed in cancer, and interactions between HIF1-α and the vascular endothelial growth factor (VEGF) were found to perform a role in angiogenesis." (PMID 29487724, 2018). "For this reason, pharmaceutical approaches targeting HIF-1α have shown promise in sensitizing radiation-resistant cancer cells to radiotherapy." (PMID 29891977, 2018). "CRC is one of the cancers in which HIF1-α subunit is overexpressed from the early stages of carcinogenesis." (PMID 29351242, 2018).
cancer (continued). "From a metabolic point of view, HIF-1α aberrant activation underpins the so-called “Warburg effect”: the preferential glycolytic consumption of glucose in cancer cells, which takes place also under normal oxygen tension." (PMID 30234010, 2018). "After HIF-1α is decreased in cancer cells, the Warburg effect in the same cells is decreased as well." (PMID 29609556, 2018). "SETD8 was also reported to reprogram cancer cell metabolism via hypoxia-inducible factor-1α (HIF-1α) mediated process by stabilizing HIF-1α protein through post-transcriptional regulation." (PMID 30002791, 2018). "Only a few minutes of hypoxia induces the expression of HIF-1α proteins in the human epithelial carcinoma cell line HeLaS3, and after 1 hour of anoxia, HIF-1α protein expression reached its maximum level, and this maximum level was maintained for 4 hours." (PMID 29775479, 2018). "Because HIF-1α stimulates cancer cell motility and invasiveness under hypoxia, the inhibitory effect of vanillin on cell migration increased by hypoxia was tested." (PMID 28257048, 2017). "At the level of cancer stem cells and their differentiated progenies, hypoxia and increased HIF-1α expression and activity promote up-regulation of different stemness elements and survival signaling factors." (PMID 29099748, 2017). "Seeking to develop novel cancer therapeutics, we investigated small molecules from our in-house chemical libraries to target HIF-1α." (PMID 27999195, 2017). "Cancer cells frequently express HIF-1α and thereby acquire increased glycolysis, viability, and angiogenesis." (PMID 29152137, 2017). "PKM2 is an isoform of this enzyme that is predominantly expressed in cancer cells, and its expression is induced by HIF1α." (PMID 28423551, 2017). "On the other hand, studies applying 0.1–1% oxygen concentrations, reported that HIF-1α stabilizes in Rho zero cancer cells or upon rotenone treatment, and Gong and Agani demonstrated that, in near-anoxic conditions, HIF-1α is stabilized despite OXPHOS damage." (PMID 29230384, 2017). "To date, several studies have suggested a relationship between HIF-1α and survivin in several types of cancers." (PMID 28476028, 2017). "The CK2 inhibitor CX-4945 exhibits anticancer activity by down-regulation of PI3K/Akt, p21 and HIF-1α and by that affects the transcriptional regulation of factors involved in cancer proliferation, angiogenesis and pro-inflammatory cytokine production." (PMID 27906674, 2017). "It has been shown that re-expression of semphorin 3A in cancer cells improves the cancer tissue oxygenation and reduces the anti-angiogenic therapy-induced activation of HIF1α leading to enhanced therapeutic effects." (PMID 28447025, 2017). "Alternatively, it induces HIF-1α protein accumulation in different cancer cell lines in an oxygen-independent manner via ROS and Akt/p70S6K signaling activation, promoting the transcription of VEGF and Glut-1 genes." (PMID 28664158, 2017). "The HIF-1α/β dimer subsequently binds to hypoxia-response elements and modulates the transcription of several target genes, which are favor cancer progression (e.g., angiogenesis, glucose metabolism, cell proliferation, apoptosis, invasion, and metastasis)." (PMID 28977888, 2017). "The reduction of NHE1 protein expression by hypoxia is consistent with recent work in which 48 h of 2% hypoxia or exposure to the HIF-1α stabilizer Dimethyloxaloylglycine (DMOG) reduced NHE1 protein levels in some cancer cell lines." (PMID 28806945, 2017). "Increased levels of HIF-1α have been demonstrated in the majority of primary human cancers and their metastases, and they were shown to be related to poor prognosis and treatment failure." (PMID 28380438, 2017).